MSTN (myostatin)
Diseases named in the same sentence as MSTN in open-access papers (continued):
Sharing a sentence is not in itself a finding about the gene and the disease.
muscular dystrophy (continued). "Myostatin inhibition via liver targeted gene transfer is highly adaptable to future gene therapy studies and has the potential to attenuate muscular dystrophy in large animal models." (PMID 20161803, 2010). "While there has been considerable interest in utilizing myostatin inhibition to ameliorate muscular dystrophy and other disorders, comprehensive long term studies of postnatal myostatin inhibition have not yet been reported." (PMID 20161803, 2010). "Clinical trials using myostatin inhibition via an antibody approach as a potential treatment for several types of muscular dystrophy are ongoing." (PMID 20419100, 2010). "The effectiveness of myostatin inhibition has been studied using various muscular dystrophy animal models." (PMID 19538713, 2009). "FST and FST-derived myostatin inhibitors are also effective for increasing muscle mass and ameliorating muscular dystrophy." (PMID 19538713, 2009). "Myostatin also has therapeutic applications in muscle-related diseases, such as muscular dystrophy, where inhibiting myostatin may help build muscle mass." (PMID 40427596, 2025). "Although the clinical failures of muscular dystrophy-targeting drugs have branded MSTN inhibitors as a fruitless endeavor, recent advancements in inhibitor application and design offer promising prospects for developing viable MSTN therapeutics." (PMID 39340593, 2025). "Genetic manipulation of myostatin has emerged as a promising approach for developing therapeutic strategies for muscle disorders, including cachexia, muscle wasting, muscle degeneration and muscular dystrophies." (PMID 39982358, 2025). "On the other hand, in a study conducted in mice with induced muscular dystrophy, the inhibition of myostatin through the expression of the follistatin transgene resulted in early improvements in histopathology, but, in the long term, muscle degeneration increased." (PMID 38893612, 2024). "Interestingly, sh‐CILP2 also significantly decreased the expression of muscular dystrophy proteins: Atrogin‐1, MuRF‐1 and Myostatin." (PMID 39385717, 2024). "If the application of myostatin inhibition to the muscular dystrophies is deemed futile, the approach may be more advantageous in subjects with a healthy muscular phenotype but where other factors, such as immobilization, induce muscular atrophy and wasting." (PMID 33802348, 2021). "If so, myostatin inhibition in patients with muscular dystrophy may provide short-term benefits in terms of increasing muscle growth but may have the long-term effect of accelerating disease progression." (PMID 26206886, 2015). "In this study, we sought to apply the Cole impedance parameters to assess muscle hypertrophy and functional enhancement induced in wild type (wt) and muscular dystrophy (mdx) animals treated with the activin type IIB receptor myostatin inhibitor RAP-031 (Acceleron Pharma, Cambridge, MA, USA)." (PMID 26485280, 2015). "In fact, a premature initiation of the myostatin-mediated protein degradation as presented in this study may in part explain why patients with severe muscular dystrophy and significant ongoing regeneration still experience progressive muscle wasting." (PMID 24963862, 2014). "Although clinical trials of myostatin inhibition are being considered for individuals with muscular dystrophy, such patients would have to be treated throughout their lives and the risks associated with chronic treatment are currently unknown." (PMID 24504412, 2014). "MSTN is of special interest to scientists because elucidating its biology may help provide therapies or cures for muscular dystrophy." (PMID 25013748, 2014). "To date, myostatin has been widely characterised as a potent negative regulator of skeletal muscle mass and methods to inhibit myostatin function as a potential therapeutic treatment for increasing muscle mass in diseases such as muscular dystrophy and cancer cachexia have been explored." (PMID 25390640, 2014).
muscular dystrophy (continued). "Many therapeutic approaches using myostatin attenuation have been conducted in muscular dystrophy." (PMID 25221510, 2014). "In contrast, myostatin blockade did not attenuate the pathology in a mouse model of merosin-deficient muscular dystrophy." (PMID 25221510, 2014). "In addition, it has been reported that myostatin inhibition decreases fibrosis after muscle injury, and in genetic models of muscular dystrophy." (PMID 23155423, 2012). "That myostatin inhibition does not improve severe muscular dystrophy is not surprising as myostatin cannot correct the underlying genetic defect." (PMID 20161803, 2010). "As the muscular dystrophies result in progressive pathology of skeletal muscle, long term studies are crucial to determine if proposed treatments will correct the pathology over time and to assess the effect of myostatin inhibition on cardiac function." (PMID 20161803, 2010). "Hence myostatin based therapies hold great promise for the muscular dystrophies due to their ability to increase fiber size, enhance regeneration and regulate muscle fibrosis." (PMID 20161803, 2010). "For the muscular dystrophies, myostatin inhibition could be utilized to augment correction of the primary defect by promoting short term gains of muscle mass." (PMID 20161803, 2010). "Myostatin is regarded as a good drug target since therapeutics that stimulate skeletal muscle growth may be useful for muscle-wasting conditions such as muscular dystrophy, sarcopenia and cachexia." (PMID 19538713, 2009). "In the last decade, the blockade of myostatin has been represented an ideal tool to attenuate muscle wasting related to diseases, and there is a multi center clinical trial on adult patients with muscular dystrophy underway." (PMID 19412331, 2007). "Muscle hypertrophy, swallowing disorders, and gait abnormalities are clinical signs common to many muscle diseases, including muscular dystrophies, non-dystrophic myotonias, myopathies associated with deficiency of myostatin, and acquired inflammatory myopathies." (PMID 38473107, 2024). "Since the initial discovery of myostatin as a potent inhibitor of muscle growth, intense effort has been invested to block myostatin actions to treat muscle-wasting diseases, with therapeutic promise in ameliorating muscular dystrophies through pharmacological inhibition." (PMID 38731986, 2024). "In addition, inhibition of myostatin in mdx mice significantly attenuated disease severity of muscular dystrophy, suggesting that myostatin may serve as a therapeutic target for the treatment of DMD." (PMID 35935842, 2022). "Similarly, the levels of decorin and biglycan, components of the ECM that interact with cytokines such as TGF-β1, as well as modulations of MAPK and myostatin signaling, are altered in various forms of muscular dystrophies including congenital MD, Emery-Dreifuss MD (EDMD) and Becker MD." (PMID 21798096, 2011). "The first study in a population of muscular dystrophy patients (DMD, BMD, LGMD) receiving myostatin inhibitors was a phase I/II trial with MYO-029 (stamulumab, Wyeth Pharmaceuticals, now Pfizer)." (PMID 33802348, 2021). "Inhibition of MSTN is considered as a promising therapy for muscle-wasting disorders, including Duchenne muscular dystrophy (DMD), a lethal and common form of muscular dystrophy affecting ∼1 in 5000 newborn boys worldwide." (PMID 27733450, 2017). "Intriguingly, myostatin inhibition using MYO-029 (Stamulumab) was tested in a prospective, randomized, placebo-controlled US phase I/II trial in 116 adults with muscular dystrophy such as BMD, fascioscapulohumeral muscular dystrophy (FSHD), and LGMD." (PMID 25221510, 2014). "We injected a nanoparticle complex containing myostatin-siRNA and ATCOL (Mst-siRNA/ATCOL) into the masseter muscles of mutant caveolin-3 transgenic (mCAV-3Tg) mice, an animal model for muscular dystrophy." (PMID 23717655, 2013).
muscular dystrophy (continued). "The aim of this study is to evaluate the effectiveness of ATCOL-mediated local administration of myostatin-targeting siRNA into skeletal muscles in LGMD1C model mice, and to evaluate this method as a future treatment for muscular dystrophy." (PMID 23717655, 2013). "Prior trials for myostatin inhibitors have displayed safety in use for patients with muscular dystrophies; however, they have not displayed significant clinical benefits to warrant active treatments." (PMID 40717734, 2025). "Wagner outlined very well different reasons why MSTN inhibition did not hold what preclinical data promised in muscular dystrophy." (PMID 33546660, 2021). "Recent studies have shown that synthetic peptides containing 29 or 24 amino acids from the mouse MSTNpro were sufficient to suppress MSTN activity in vitro and to increase muscle mass in mice of muscular dystrophy model." (PMID 30998775, 2019). "There were also no important improvements in muscle strength by MSTN inhibition in muscular dystrophy patients in another study, although there was an amelioration in muscle function at a cellular level." (PMID 30717377, 2019). "In a clinical trial in adult patients with muscular dystrophy, MSTN-neutralizing antibodies were well tolerated but had no beneficial effects on the muscles." (PMID 27733450, 2017). "Additional questions have been raised about potential exhaustion of the pool of muscle progenitor cells (i.e., satellite cells) undergoing multiple divisions in the absence of myostatin in muscular dystrophy." (PMID 27047655, 2016). "Indeed, myostatin inhibition using MYO-029 was tested in a prospective, randomized, and US phase I/II trial in 116 adults with muscular dystrophy such as Becker muscular dystrophy, facioscapulohumeral muscular dystrophy, and limb-girdle muscular dystrophy." (PMID 22500226, 2012). "A clinical trial utilizing a neutralizing antibody directed at myostatin did not improve muscle function or increase muscle mass in adult patients with muscular dystrophy." (PMID 20161803, 2010). "However, several MSTN inhibitors failed to achieve efficacy in clinical trials for the treatment of muscular dystrophy." (PMID 35457038, 2022). "Moreover, there was no amelioration in muscle strength or function in muscular dystrophy patients in one phase I/II trial of a MSTN antibody." (PMID 30717377, 2019). "In previous clinical trials with a selective anti-myostatin antibody, MYO-029, no improvement in endpoints related to muscle strength and function was seen in adult muscular dystrophy patients." (PMID 29121992, 2017).
diabetes (64 papers, 2009 to 2026). "Inhibition of myostatin, a negative regulator of muscle mass, was explored as a druggable target to improve the musculoskeletal phenotype associated with insulin-deficient diabetes in female mice." (PMID 40575255, 2025). "Myostatin inhibition when used in conjunction with insulin treatment improves muscle mass and trabecular bone properties in a mouse model of insulin-deficient diabetes in female mice." (PMID 40575255, 2025). "Among those, low-intensity pulsed ultrasound for diabetes associated muscle atrophy in rats was beneficial as it downregulated myostatin and AcvRIIB expression in skeletal muscle." (PMID 40575255, 2025). "This is the first comprehensive study to report on the effects of myostatin pharmacologic inhibition on an insulin‐deficient model of diabetes and describe these effects on both muscle and bone." (PMID 38025035, 2023). "We found that Wnt pathway–related genes are downregulated with insulin‐deficient diabetes, whereas systemic myostatin inhibition with REGN647 resulted in lower Dkk3 gene expression." (PMID 38025035, 2023). "Myostatin/ASM ratio was negatively associated with hs-CRP in men, while Myostatin/ASM ratio in women was negatively associated with diabetes and handgrip strength." (PMID 34299795, 2021). "Hs-CRP was associated with serum myostatin levels in men, while diabetes in women was associated with serum myostatin levels." (PMID 34299795, 2021). "Further, an 8-week treatment with a polyclonal anti-myostatin antibodies protected diet-induced obese rats from diabetes-associated femoral bone microarchitecture and strength degradation." (PMID 33854530, 2021). "Myostatin has been suggested as a good candidate for therapeutic intervention in diseases with loss of muscle mass, including diabetes." (PMID 19668377, 2009). "Taken together, these results support the hypothesis that myostatin inhibition could prevent muscle atrophy in a condition of insulin‐deficient diabetes." (PMID 38025035, 2023). "Myostatin, a myokine whose increased expression is associated with muscle‐wasting diseases, has not been reported in humans with T1D but has been demonstrated to be elevated in preclinical diabetes models." (PMID 32652899, 2020). "In accordance, a positive association between plasma and muscle myostatin was only observed in the healthy controls, which may suggest an alteration in the regulatory mechanism with diabetes." (PMID 22615949, 2012). "Nonetheless, it is imperative to also consider the contributions of other myokines and their interactions with MSTN in the context of bone metabolism disorders that arise as complications of diabetes affecting the musculoskeletal system." (PMID 40136413, 2025). "Several studies have evaluated various treatments for diabetes-induced muscle atrophy, with some specifically targeting the myostatin pathway in skeletal muscle and the Wnt pathway in bone." (PMID 40575255, 2025). "In multivariate analysis, myostatin remained associated with an increased risk of AV access events after adjusting for confounding factors: BMI, SBP, and history of diabetes." (PMID 40278657, 2025). "This is consistent with the literature, demonstrating that myostatin upregulates glycolytic fibers and diabetes preferentially targets glycolytic fibers (and, thus, neither would impact fatigability)." (PMID 40429969, 2025). "Further animal studies showed that decreased myostatin expression improved glucose uptake even in diabetes." (PMID 38398421, 2024). "Children with type 1 diabetes mellitus (T1DM) exhibited significantly elevated serum myostatin levels compared to healthy subjects in some studies." (PMID 38398421, 2024). "Skeletal muscle fiber analysis from gastrocnemius showed trends for higher Type I fiber percentage with diabetes (p = 0.051) and treatment with myostatin antibody trended toward higher Type I fiber percentage in ND mice (p = 0.057)." (PMID 38025035, 2023).
diabetes (continued). "Hs-CRP, eGFR by cystatin C, and ASM index were associated with serum myostatin level in men, while diabetes, eGFR by cystatin C and ASM index in women were associated with serum myostatin level." (PMID 34299795, 2021). "On the other hand, it suggests FMOD inhibits aging by downregulating genes involved in muscle aging, diabetes, and intracellular lipid accumulation or by indirectly inhibiting their expressions by suppressing the activity of MSTN protein." (PMID 34440852, 2021). "An increase in myostatin muscle expression was reported in patients with diabetes, prediabetes, and in close relatives of diabetic patients." (PMID 34795636, 2021). "Regulatory roles of myostatin have now been discovered in aging, cancer cachexia, insulin sensitivity, diabetes, and in cardiac tissue where myostatin influences inflammation." (PMID 33854530, 2021). "Gallagher and colleagues have included an excellent set of participant data as part of GSE18732 that allowed for correlational analyses between myostatin mRNA expression and variables related to IR/diabetes and overall metabolic health." (PMID 32652899, 2020). "Our data revealed that myostatin plasma level was elevated as a function of diabetes, and this was corroborated by an elevation in the expression of its mRNA in muscles." (PMID 30510624, 2018). "Circulating myostatin is commonly elevated in patients with conditions such as chronic liver and kidney disease, diabetes mellitus, and human immunodeficiency virus infection, and in the elderly." (PMID 28742154, 2017). "Most importantly, myostatin acts as a regulator of pro-inflammatory factors in some diseases, e.g., chronic kidney disease and type 2 diabetes mellitus." (PMID 29276516, 2017). "Similar attenuation of TGF-beta receptor signaling by systemically administered small molecule has greatly improved muscle regeneration at the onset of full diabetes, where muscle stem cell responses are blocked by an upregulation of myostatin." (PMID 26540176, 2015). "In our study, increased myostatin expression is inversely related to insulin sensitivity in diabetes." (PMID 24454989, 2013). "By using this assay, it was suggested for example, that serum myostatin levels are increased or decreased in patients with chronic heart failure, increased or unchanged in diabetes mellitus type 2 and perhaps reduced in adult patients with Pompe disease." (PMID 24260393, 2013). "When the data from the patients with diabetes and the control subjects were combined, plasma and muscle myostatin levels were similar in men and women (P = 0.5 and P = 0.2 respectively)." (PMID 22615949, 2012). "According to our results for the MSTN/Akt signaling pathways, the protein expressions of MSTN in muscles were decreased by LIPUS in diabetes rats, indicating that the inhibition of MSTN may contribute to improvements in T1DM-induced skeletal muscle atrophy." (PMID 41154746, 2025). "We investigated whether administration of an inhibitory myostatin antibody (MyoAb) in streptozotocin-induced diabetes in female mice is protective for skeletal muscle and bone." (PMID 40575255, 2025). "Inhibition of MSTN is beneficial for metabolic syndrome and diabetes in various ways." (PMID 39340593, 2025). "In multivariate analysis, myostatin > 2170 pg/mL remained significantly associated with an increased risk of AV access events (Adjusted HR = 1.90, 95% CI [1.02–3.55]; p = 0.044) when adjusted for BMI, SBP before dialysis > 140 mmHg, and history of diabetes." (PMID 40278657, 2025). "However, myostatin deletion preserved maximum force generation even after diabetes was induced, as the T1D-Myo KO mice showed a preservation of function, particularly with regard to muscle torque production." (PMID 40429969, 2025). "In addition to its direct relationship with diabetes, MSTN is also involved in the occurrence and development of diabetes complications." (PMID 37288303, 2023).